WT1 (WT1 transcription factor)
Diseases named in the same sentence as WT1 in open-access papers (continued):
Sharing a sentence is not in itself a finding about the gene and the disease.
pulmonary fibrosis (7 papers, 2014 to 2025). Chronic progressive interstitial lung disorder characterized by the replacement of the lung tissue by connective tissue, leading to progressive dyspnea, respiratory failure, or right heart failure. "In vivo, overexpression of WT1 in fibroblasts exacerbated fibrosis in bleomycin-induced pulmonary fibrosis models, as evidenced by increased collagen deposition, myofibroblast accumulation, and impaired lung function." (PMID 40493404, 2025). "Given that TGF-β and TGF-α are known positive regulators of fibroblast activation in the pathogenesis of pulmonary fibrosis, we sought to identify the potential role of these growth factors in the upregulation of WT1 in fibroblasts." (PMID 40493404, 2025). "Recent studies from our lab and others showed that WT1 upregulation in fibroblasts is involved in fibroblast activation and the pathogenesis of pulmonary fibrosis." (PMID 34520400, 2021). "During TGF-α–induced pulmonary fibrosis, WT1-positive fibroblasts have been shown to accumulate in distal fibrotic lesions, similar to SOX9-positive fibroblasts." (PMID 34520400, 2021). "Our result showing decreased expression of WT1 in both waterpipe and dual smoker groups points towards the possible emergence of pulmonary fibrosis amongst these users." (PMID 33290406, 2020). "Recent studies from our laboratory have shown that WT1 is upregulated in mesenchymal cells of subpleural fibrotic lung lesions and that it contributes to pulmonary fibrosis pathogenesis." (PMID 32761869, 2020). "Overexpression of WT1 in fibroblasts augments pulmonary fibrosis in aged mice." (PMID 40493404, 2025). "Similarly, in a mouse model of TGF-α–induced pulmonary fibrosis, WT1+ myofibroblasts have been shown to accumulate in thickened subpleural fibrotic lesions due to transformation of fibroblasts to myofibroblasts through MMT." (PMID 40493404, 2025). "Thus, our findings indicate that WT1 overexpression in fibroblasts of aged mice contributes to myofibroblast accumulation and collagen deposition during bleomycin-induced pulmonary fibrosis." (PMID 40493404, 2025). "However, the mechanisms by which WT1 contributes to myofibroblast accumulation in pulmonary fibrosis have remained unclear." (PMID 40493404, 2025). "Several recent studies have shown that WT1 induces proliferation, MMT, and ECM production in fibroblasts and that the loss of 1 allele is sufficient to attenuate both TGF-α– and bleomycin-induced pulmonary fibrosis." (PMID 40493404, 2025). "This refined understanding highlights WT1 as a potential therapeutic target in pulmonary fibrosis." (PMID 40493404, 2025). "Overexpression of WT1 in fibroblasts augments bleomycin-induced pulmonary fibrosis." (PMID 40493404, 2025). "Notably, the haploinsufficiency of WT1 was sufficient to attenuate fibroproliferation, myofibroblast accumulation, and collagen deposition in both TGFα- and bleomycin-induced pulmonary fibrosis in vivo." (PMID 36769178, 2023). "We demonstrated that the TGF-α/WT1 axis was involved in SOX9 upregulation in pulmonary fibrosis." (PMID 34520400, 2021). "Our previous studies demonstrate upregulation of multiple growth factors including TGFβ, IL-6, IL-13, amphiregulin and epiregulin in distinct mesenchymal cell subsets such as fibrocytes, lung resident fibroblasts and WT1-positive myofibroblasts during TGFα-induced pulmonary fibrosis." (PMID 31156440, 2019). "The observed upregulation of WT1 in IPF fibroblasts suggests a unique and previously unrecognized role for this developmental transcription factor in lung fibrosis." (PMID 40493404, 2025). "Both in vitro and in vivo studies using loss-of-function and gain-of-function models demonstrate that WT1 functions as a positive regulator of ECM gene expression, fibroproliferation, myofibroblast transformation, and pulmonary fibrosis." (PMID 40493404, 2025).
pulmonary fibrosis (continued). "Taken together, our findings demonstrate the profibrotic effects of WT1 upregulation in promoting fibroblast proliferation, survival, and ECM production during bleomycin-induced pulmonary fibrosis." (PMID 40493404, 2025). "Fibroblast-specific overexpression of WT1 augmented fibroproliferation, myofibroblast accumulation, and ECM production during bleomycin-induced pulmonary fibrosis in young and aged mice." (PMID 40493404, 2025). "We demonstrated that WT1 is downregulated in the postnatal stages of lung development but is upregulated in mesothelial cells in IPF and in a mouse model of TGFα-induced pulmonary fibrosis." (PMID 36769178, 2023). "Previous studies have identified the important roles of WT1 in both TGF-α– and bleomycin-induced pulmonary fibrosis, whereas the role of SOX9 has remained unclear." (PMID 34520400, 2021). "Recent studies from our laboratory have shown that WT1 is upregulated in activated fibroblasts, and it coincides with the increase in profibrotic gene networks, including Sox9, during TGF-α–induced pulmonary fibrosis." (PMID 34520400, 2021). "Compared to control siRNA, knockdown of WT1 was sufficient to attenuate the expression of AURKB in lung fibroblasts isolated from both IPF and a mouse model of TGFα‐induced pulmonary fibrosis." (PMID 32761869, 2020). "We identified a role for WT1 in AURKB expression and AURKB‐driven transcripts involved in proliferation and survival of fibroblasts in the pathogenesis of pulmonary fibrosis." (PMID 32761869, 2020). "Collectively, these findings suggest that WT1 functioned as a negative regulator of fibroblast apoptosis, consistent with a role for WT1 in fibroblast survival, accumulation, and excess ECM production in the pathogenesis of pulmonary fibrosis." (PMID 40493404, 2025). "However, more recent studies have demonstrated that WT1 is upregulated in both mesothelial cells and (myo)fibroblasts in IPF, as well as in a mouse model of TGF-α–induced pulmonary fibrosis." (PMID 40493404, 2025). "Together, our findings suggest that WT1 functions as a positive regulator of SOX9 by directly binding to the SOX9 promoter in the distal lung fibroblasts during TGF-α–induced fibroblast activation and pulmonary fibrosis." (PMID 34520400, 2021). "However, future studies are needed to evaluate possible binding partners and other molecular regulators downstream of WT1 and AURKB in fibroblast activation and pulmonary fibrosis." (PMID 32761869, 2020).
carcinosarcoma (6 papers, 2018 to 2025). A malignant tumor composed of a mixture of carcinomatous and sarcomatous elements. "Carcinosarcoma and serous histotypes showed the higher rates of WT1 IHC expression (38% and 21% respectively), followed by endometrioid and clear cell histotypes (19% and 15% respectively)." (PMID 32859123, 2020). "Approximately half of ovarian endometrioid carcinomas expressed WT1 as well as most mixed epithelial cell OvCa and most carcinosarcomas." (PMID 30057405, 2018). "The KPOSE-AdCre carcinosarcoma model is WT1 and HNF1β negative, vimentin high, and shows low T-cell infiltration and no B cells or TLSs." (PMID 40642792, 2025). "Additionally, clinical trials evaluated anti-PD-1 plus lenvatinib in WT-1-positive carcinosarcomas, although without significant findings." (PMID 40558574, 2025).
clear cell ovarian carcinoma (6 papers, 2010 to 2024). "In addition, WT1, as one of the representative genes regulated by the ER-α signaling pathway, is downregulated in patients with endometriosis, consistent with the loss of WT1 expression in ovarian clear cell carcinoma." (PMID 29780815, 2018). "In terms of immunohistochemistry, ovarian clear-cell carcinoma typically shows strong positivity for hepatocyte nuclear factor 1β, while it is consistently negative for estrogen receptor (ER), progesterone receptor (PR), and WT-1 in over 95% of cases." (PMID 40729263, 2024).
congenital diaphragmatic hernia (6 papers, 2016 to 2024). A posterolateral defect of the diaphragm that allows passage of abdominal viscera into the thorax, leading to respiratory insufficiency and persistent pulmonary hypertension with high mortality. "In humans, germline WT1 mutations lead to the eponymous pediatric cancer, genitourinary anomalies, and, in some cases, congenital diaphragmatic hernia and heart disease." (PMID 28289143, 2017). "WT1 knockout mice showed hypoplastic lung phenotype and the defects of human mesothelial cells by congenital diaphragmatic hernia (CDH), also known to develop lung hypoplasia." (PMID 39376629, 2024). "WT1 plays a crucial role in diaphragm morphogenesis as confirmed by the development of congenital diaphragmatic hernia in wt1-null mouse embryos." (PMID 34198563, 2021). "WT1 null mice will be unable to develop kidneys and gonads; will exhibit congenital diaphragmatic hernia; and will die in utero, on average, at ~13.5 embryonic days, presumably due to cardiac problems, while also manifesting hypoplastic lungs, splenic agenesis and adrenal gland agenesis." (PMID 35453662, 2022). "Mice with the loss of WT1 do not have kidneys or gonads, exhibit congenital diaphragmatic hernia, and die due to cardiac problems." (PMID 34205452, 2021).
end-stage renal disease (6 papers, 2009 to 2026). "The WT1 mutation, which exhibits a wide range of phenotypes, leads to end-stage renal failure in early infancy." (PMID 41142893, 2025).
Meacham syndrome (6 papers, 2016 to 2025). Meacham syndrome is a multiple malformation syndrome characterized by congenital diaphragmatic abnormalities, genital defects and cardiac malformations. "Meacham syndrome, the rarest WT1-associated illness, encompasses genitourinary, cardiac, and pulmonary abnormalities and is often lethal in early life." (PMID 40426774, 2025). "Later, a role for WT1 in some cases of congenital diaphragmatic hernia associated with the Meacham syndrome phenotype had been suggested." (PMID 34299295, 2021). "Rare genetic variants in WT1 have also been reported in association with Meacham syndrome (MIM 608978), characterized by 46,XY gonadal dysgenesis, congenital diaphragmatic hernia, and congenital heart disease." (PMID 32493750, 2020). "In a number of Meacham syndrome patients, heterozygous missense mutations in the C–terminal zinc finger domains of WT1 could be identified, suggesting that at least some cases displaying phenotypes of Meacham syndrome are caused by mutations at the WT1 locus." (PMID 34299295, 2021).
prostate tumor (6 papers, 2010 to 2023). "While there have been reports of WT1 expression in prostate, our results demonstrate the most complete evidence of elevated WT1 expression at both mRNA and protein levels in prostate tumors." (PMID 20426842, 2010). "Evidence was provided to support a tendency towards reduced expression in prostate tumor tissue at DLK1, PLAGL1, SLC22A18, with less conclusive expression data for WT1 and TP73." (PMID 23890537, 2013). "We have previously reported the presence of one such transcription factor, WT1 in high Gleason grade prostate tumor tissues, and its absence in non-neoplastic or benign prostatic hyperplasia tissues." (PMID 23298185, 2013).
renal agenesis (6 papers, 2011 to 2021). Renal agenesis (RA) is a form of renal tract malformation characterized by the complete absence of development of one or both kidneys (unilateral RA or bilateral RA respectively), accompanied by absent ureter(s). "The authors proceeded to knockdown Wt1 with siRNA and showed that re-aggregated cells formed fewer nephron structures, but produced UB epithelia in the same manner as untreated cells, mirroring previous studies showing that genetic knockouts of Wt1 causes renal agenesis." (PMID 28393110, 2016). "Shortly after, re-evaluation of autopsy data from fourteen additional fetuses with combined renal agenesis and cardiac anomalies revealed abnormalities of Wt1 expression, mostly in liver mesenchymal cells." (PMID 34299295, 2021). "WT1 misexpression has been reported in autopsy findings from two human fetuses, displaying congenital pulmonary airway malformation, bilateral renal agenesis, and congenital heart defects." (PMID 34299295, 2021). "Wt1 is crucial for kidney development as the conventional Wt1-null embryos suffer from renal agenesis." (PMID 22216009, 2011). "Liver mesenchymal cells were abnormally formed in renal agenesis fetuses with reduced WT1 liver mesothelial expression, generally lacking stellate cells that express cRBP-1." (PMID 26265759, 2015).
Renal Wilm’s Tumor (6 papers, 2016 to 2025). "We were interested to study the effect of Dapagliflozin and Dapagliflozin-Saxagliptin combination groups on podocyte health by quantifying the exosome expression for Nephrin, Renal Wilm’s Tumor (WT-1) and Podocalyxin like protein 1( PODXL) in urine samples." (PMID 39865301, 2025). "Recently, frameshift extension mutations in CALR (encoding calreticulin) were identified in myeloproliferative neoplasms and WT1 extension mutants have been described in Wilms kidney tumours." (PMID 27588951, 2016). "Review of all reported WT1 negative adult renal Wilms tumour cases in the current literature." (PMID 40177273, 2025).
squamous cell carcinoma (6 papers, 2015 to 2026). A carcinoma arising from squamous epithelial cells. "Only two of the WT1 positive cancers were positive for CA125/MUC16, and only 3 of the TP63 positive samples expressed CK17 and CK5, characteristic of squamous carcinoma." (PMID 25885340, 2015).
colon cancer (5 papers, 2013 to 2023). "In addition, as WT1 is one of the HIF downstream oncogene targets, it will be mandatory to monitor the development and progression of WT1-mediated cancers including ovarian, breast, lung, uterine, colon cancers, pleural mesothelioma and hematologic malignancies." (PMID 35465313, 2022).
cyst (5 papers, 2016 to 2026). A sac-like closed membranous structure that may be empty or contain fluid or amorphous material. "The unusual cystic kidney appearance in our patients highlights the need to explore an underlying second modifier as a potential mechanism linking WT1 variants and cyst formation." (PMID 41450889, 2025). "By immunohistochemistry, estrogen receptor (ER), progesterone receptor (PR), PAX-8, and WT1 were positive in the epithelial lining of the cyst, lending support to a possible Müllerian origin." (PMID 28070193, 2016). "The characteristic microscopic appearance of a single layer of cuboidal mesothelial cells lining the cyst wall, along with positive staining for specific mesothelial markers such as calretinin, WT-1, mesothelin, and HBME, aids in the diagnosis of pelvic mesothelial cysts." (PMID 39759741, 2024). "•The immunopositivity for WT1 plays a great role in explaining the cyst’s behavior." (PMID 31760217, 2019). "The cyst lining is typically positive for estrogen receptor (ER), progesterone receptor (PR), PAX-8, and WT1 immunohistochemical stains." (PMID 28070193, 2016). "In this instance, the cyst was located in the upper thigh and showed strong staining not only for ER and PR but also for PAX-8 and WT1." (PMID 28070193, 2016). "Histopathology revealed a cyst lined by cuboidal epithelium, positive for Claudin4, estrogen receptor, Wilms' Tumor 1 (WT1), and Paired box gene 8 (PAX8), and negative for Calretinin, findings consistent with a Müllerian duct cyst." (PMID 41728454, 2026).
developmental delay (5 papers, 2020 to 2025). "Our data reveal a developmental delay in DMD organoids, with a significantly higher proportion of embryonic myotubes and reduced PAX7+ progenitor pools (WT1: 48.49% vs. DMD1: 24.91%)." (PMID 40643552, 2025). "The mouse data, which showed an increase in the number of Wt1-positive cells, also failed to discriminate whether this was a result of developmental delay or increased fate assignment." (PMID 32357958, 2020). "Among the four patients with large deletions encompassing the entire WT1 gene, one did not have AN as their deletion did not encompass the PAX6 gene and one female patient had only AN and no GU abnormalities, with four having developmental delay." (PMID 34608521, 2022).
endometriosis (5 papers, 2018 to 2023). The growth of functional endometrial tissue in anatomic sites outside the uterine body. "Immunostaining evidence suggests WT1 is downregulated in the eutopic endometrium from women with endometriosis but is expressed in neurons of deep endometriosis." (PMID 37587191, 2023). "The product of H3K27me3 gene sets and one of its target proteins, WT1, were found enriched in neighboring endometriosis, but silenced in OCCC lesion, which suggests that epigenetic reprogramming transformed the endometriotic cells to a pluripotent stage as OCCC." (PMID 29941051, 2018). "There were several genes strongly expressed in endometriosis tissue: EPCAM, KRT18, WT1, MUC16, MUC1, and ESR1, if compared to the endometrial cells from healthy controls." (PMID 31717910, 2019). "WT1, CK20 and CDX2 were scarcely expressed and were not different between ovarian SMBT with and without endometriosis." (PMID 35387670, 2022).
gynecological cancers (5 papers, 2012 to 2023). "The wild-type WT1 gene has been characterized as an oncogene in many malignancies and is specifically highly expressed in various gynecological cancers." (PMID 34134781, 2021). "We evaluated the prognostic value of WT1 in gynecological cancers through meta-analysis to elucidate its potential use in practice." (PMID 29995811, 2018). "For other gynecological cancers except OC, the WT1's prognostic value was evaluated only in univariate model (metaHR = 1.96, 95% CI = 1.03–3.72)." (PMID 29995811, 2018). "The hazard ratio (HR) with its 95% confidence interval (CI) were calculated to investigate prognostic of WT1 expression in patients with gynecological cancer." (PMID 29995811, 2018). "It suggests that WT1 may be used as predictor to evaluate the prognosis of patients with high stage of gynecological cancer." (PMID 29995811, 2018). "In summary, this meta-analysis indicates that WT1 maybe a potential marker to predict the prognosis and progression for patients with gynecological cancer." (PMID 29995811, 2018). "From our point of view, in univariate analysis WT1 can becomes an independent unfavorable predictor for DSS, DFS/RFS/PFS and it can also predict OS in gynecological cancers." (PMID 29995811, 2018). "Herein we test the immunogenicity of 24 different peptides, from three leading vaccine target proteins in gynecological cancers: the E7 protein of human papilloma virus (HPV); Wilms Tumor antigen 1 (WT1) and survivin (SV), in PSNP conjugate vaccines." (PMID 30631324, 2018). "In both CK7 + /CK20 − /ER + (1 case) and CK7 + /CK20 + /ER + (2 cases) adenocarcinomas, PAX8/WT1 expression was performed to rule out gynecological cancers." (PMID 36346458, 2023). "The oncogenic role of Wilms’ tumor 1 (WT1) which is regarded as a promising target antigen for cancer immunotherapy has been demonstrated in many types of cancer, but the relationship between expression of WT1 and the prognosis value in gynecological cancer reminds unclear." (PMID 29995811, 2018).